FGFR3 (fibroblast growth factor receptor 3)
Diseases named in the same sentence as FGFR3 in open-access papers (continued):
Sharing a sentence is not in itself a finding about the gene and the disease.
lung cancer (continued). "Recently, FGFR3-transforming acidic coiled-coil 3 (TACC3) fusions have been identified in glioblastoma, head and neck carcinoma, and lung cancer, as well as urothelial cancer (UC)." (PMID 27930669, 2016). "Additionally, in lung cancer, PRMT5 suppresses miR-99 through H4R3me2s, upregulating FGFR3 and activating ERK1/2 and AKT pathways to promote tumor progression." (PMID 41204384, 2025). "Several gatekeeper mutations in the FGFR family have been reported in preclinical studies in several cancer models, including FGFR1 V561M in lung cancer, FGFR2 V565I/N550K/V564F in endometrial cancer and cholangiocarcinoma, FGFR3 V555M in myeloma and FGFR4 V550L/V550E in rhabdomyosarcoma." (PMID 34068816, 2021). "Among other FGFR3 fusions, FGFR3–BAIAP2L1 has been described in bladder and lung cancer." (PMID 32962091, 2020). "FGFR3, LBP, LECT2, and DYNC1I1 were distinguishable markers in lung cancer." (PMID 32528533, 2020). "Similar to this HNSCC study, FGFR3 protein expression holds no prognostic value in non‐small cell lung cancer." (PMID 26711175, 2016). "In NSCLC tissues, many onco-miRs/tumor suppressor-target or tumor suppressor-miRs/onco-target pathways have been demonstrated to participate in the tumorigenesis of lung cancer, including miR7/BCL2 axis, miR-99b/FGFR3 axis, miR-101/EZH2 axis, miR-192/RB1 axis and miR-196/HOXA5 axis." (PMID 25012722, 2014). "In our present study using lung cancer cell lines, FGFR1 is most abundant receptor of the four family proteins in afatinib-resistant clones of PC9, and there was no enhancement in expression of other FGFR family proteins FGFR2, FGFR3 and FGFR4." (PMID 25115383, 2014). "MEOX2 was uniformly higher methylated in all lung cancer samples, while the methylation of the other three genes was correlated with either the differentiation status of the tumor (MDK, LAPTM5) or with the tumor histopathological type (FGFR3)." (PMID 23086271, 2013). "Interestingly, SplitFusion detected novel fusions that have not been reported previously in lung cancer, including one squamous cell carcinoma with FGFR3::JAKMP1 fusion, one adenocarcinoma with CLIP2::BRAF fusions (two fusion isoforms in one tumor), and one adenocarcinoma with ITPR2::ETV6 fusion." (PMID 40041857, 2025). "Of these fusions, 16 (including ALK, ARAF, BRAF, FGFR1, FGFR3, RET, and ROS1) and 21 (including ABL1, GNAS, JAK2, and NRG1) were classified as either related to lung cancer, or as oncogenes that have not been reported in lung cancer, respectively." (PMID 36153311, 2022). "We also observed a strong negative correlation between PLK1 and FGFR3 in EGFR‐mutant lung cancer cohort, whereas there are no such correlations in BRAF‐mutant lung cancer." (PMID 34369083, 2021).
glioblastoma (64 papers, 2010 to 2026). The most malignant astrocytic tumor (WHO grade IV). "FGFR3 is very lowly expressed in normal brain but is highly expressed in fusion positive glioblastoma that is likely due to the loss of microRNA regulation." (PMID 39087020, 2024). "Two fusions identified as having oncogenic potential in our study had previously been associated with glioblastoma: FGFR3::TACC3 and EGFR::SEPTIN14." (PMID 36002559, 2022). "Recent histologic–molecular correlations have also focused on the phenotype associated with FGFR3 fusions in glioblastoma." (PMID 34572759, 2021). "Two fusions had previously been associated with glioblastoma: FGFR3::TACC3 and EGFR::SEPTIN14." (PMID 36002559, 2022). "In addition, FGFR3-fusion-positive glioblastomas harbored a generally lower overall mutational burden." (PMID 35955806, 2022). "The FGFR3 glioblastoma cases exhibited the most common mutations found in IDH-wild-type glioblastoma, with CDKN2A homozygous loss in all cases, followed by PTEN mutations with LOH and CDKN2B homozygous loss, in three cases, and TERT c.124C>T promoter mutation in two cases." (PMID 33853673, 2021). "The analysis of imaging data of a large set of FGFR3 fusion-positive glioblastoma revealed an association with the occurrence in the cortical-subcortical region, insular, and temporal lobe location, which might be due to the specific role of FGFRs in the development of these brain areas." (PMID 35955806, 2022). "FGFR3::TACC3 fusion-positive gliomas demonstrate a relatively favorable prognosis, with better outcomes than FGFR3::TACC3-negative glioblastomas, although still poorer than those of IDH-mutant gliomas." (PMID 40417325, 2025). "Diffuse gliomas with FGFR3::TACC3 fusion have an intermediate prognosis, with poorer survival outcomes than IDH-mutant gliomas but superior outcomes compared to FGFR3::TACC3-negative glioblastomas." (PMID 40417325, 2025). "Patients with FGFR3::TACC3 fusion-positive glioblastomas were reported to be similar in age or slightly older at diagnosis compared to those with fusion-negative glioblastomas, with variable reports regarding sex predominance." (PMID 40417325, 2025). "Diffuse gliomas with FGFR3::TACC3 fusion (F3T3 gliomas) and high-grade histological features harbor molecular stigmata and the DNA methylation profile of glioblastoma, though they are associated with slightly longer patient survival." (PMID 38730596, 2024). "Members of the receptor tyrosine kinase gene family including EGFR, MET, PDGFRA, and FGFR3 have been known to be heavily involved in the initiation and progression of glioblastoma." (PMID 39087020, 2024). "The FGFR3::TACC3 fusion was detected in one out of 72 samples of glioblastoma in the Ivy Center cohort, and 2 of 161 samples in the TCGA cohort." (PMID 39087020, 2024). "As the result of an intrachromosomal translocation on human chromosome 4p16, FGFR3-TACC3 was first discovered in glioblastoma with TACC3 fused to a slightly truncated FGFR3 with an intact kinase domain." (PMID 36780330, 2023). "Diffuse gliomas with FGFR3::TACC3 fusion have been mainly reported in the adult setting where they account for 3.1–11.8% of cases with pathological features of glioblastoma." (PMID 36647073, 2023). "Glioblastomas with FGFR3::TACC3 fusion are mainly distributed between mesenchymal and RTK2 MC subtypes." (PMID 36647073, 2023). "The same authors reported that a combination treatment of vinblastine (VBL) and mebendazole (MBZ) with TMZ was more effective in reducing the cell number when glioblastoma cells had low expression levels of FGFR3." (PMID 36132155, 2022). "With targeted sequencing for FGFR3 fusions in 51 intensely stained glioblastoma specimens, 41 harbored FGFR3 fusion gene rearrangements, leading to a sensitivity of 100% and a specificity of 88% for FGFR3-immunostaining." (PMID 35955806, 2022).
glioblastoma (continued). "The presence of a FGFR3 fusion in glioblastoma IDH wildtype is reported as a favorable prognostic factor, associated with a better overall survival compared to glioblastoma IDH-wildtype without FGFR3 fusion." (PMID 35955806, 2022). "Using FGFR3-overexpressing patients-derived cells (glioblastoma, GBM), biotin-X-DHPE and Streptavidin-coated magnetic beads were coupled to use in the solution-phage bio-panning procedure." (PMID 34207911, 2021). "NGS was performed on six F48 samples, including normal tissue, and on the four FGFR3 glioblastoma surgical specimens." (PMID 33853673, 2021). "Four of these were IDH-wild-type glioblastomas with FGFR3 alterations (FGFR3 glioblastoma), occurred in older patients (median age 67 years) and resulted in a 13.6-month median survival." (PMID 33853673, 2021). "Metabolic rewiring as occurs in IDH1mt glioblastoma has also been described as occurring in 3% of glioblastoma patients with fibroblast growth factor receptor 3 (FGFR3)–transforming acidic coiled-coil-containing protein 3 (TACC3) gene fusions." (PMID 33810170, 2021). "In particular, FGFR-TACC fusions which is clonal tumor-initiating events appear in 3% of glioblastoma for FGFR3- TACC3 fusion, confer strong sensitivity to FGFR tyrosine kinase in preclinical and preliminary clinical data." (PMID 30167084, 2018). "All patients demonstrating a PR had FGFR2 or FGFR3 translocations, and tumour types were reported as glioblastoma, UC, and endometrial cancer." (PMID 28070720, 2017). "For example, in glioblastoma, the FGFR3 (fibroblast growth factor receptor 3) gene has been shown to escape regulation by the miR-99a microRNA due to a fusion with the 3’UTR of the TACC3 (transforming, acidic coiled-coil containing) gene." (PMID 28851357, 2017). "FGFR3 fusion with TACC3 has been reported to have transforming effects in primary glioblastoma and display oncogenic activity in vitro and in vivo." (PMID 27829236, 2016). "To verify the specificity of the anti-Fgfr3 antibody, we performed RNA interference on the T98G human glioblastoma cell line, which expresses FGFR3." (PMID 25766327, 2015). "Histopathologically, diffuse gliomas with FGFR3::TACC3 fusion frequently exhibit microcalcifications, nuclear palisading, and curvilinear capillary proliferation, which have been reported to be significantly more prominent than those in FGFR3::TACC3-negative glioblastomas." (PMID 40417325, 2025). "The presence of FGFR3/TACC fusion proteins in some glioblastoma patients suggests that FGFR3 antibodies could be considered as a therapeutic option for select patients with this alteration." (PMID 37857607, 2023). "FGFR3 is very lowly expressed in normal brain and fusion negative adult glioblastoma but is highly expressed in fusion positive glioblastoma, which is likely due to the loss of microRNA regulation." (PMID 35169893, 2022). "Scientific evidence reveals that human glioblastoma is also characterized by oncogenic fusions involving the members of the FGFR3 and FGFR1 tyrosine kinases (TKs) to the transforming acidic coiled-coil (TACC) proteins, in particular TACC3 and TACC1, necessary to promote cell division." (PMID 33352931, 2020). "In this study, we enriched the functional antibodies through the additional semi-automated cell panning process using PDCs (glioblastoma, GBM) with a high level of FGFR3 expression." (PMID 34207911, 2021). "Here, we report a case of diffuse glioma with FGFR3::TACC3 fusion, characterized by striking calcifications and a diffuse infiltrative growth pattern consistent with glioblastoma, IDH-wildtype." (PMID 40417325, 2025). "Diffuse gliomas with FGFR3::TACC3 fusion constitute a distinct molecular subtype with potentially unique radiological features, particularly prominent calcifications with an infiltrative tumor growth pattern suggestive of glioblastoma, IDH-wildtype, which may serve as a useful diagnostic marker." (PMID 40417325, 2025).
glioblastoma (continued). "Histopathological examination confirmed glioblastoma, IDH-wildtype, and subsequent genetic testing revealed FGFR3::TACC3 fusion and amplification of FGFR3 gene." (PMID 40417325, 2025). "In glioblastoma, the overall prevalence of FGFR aberrations is approximately 2–8%, with FGFR3 fusions being relatively common." (PMID 41514604, 2025). "The four RTK subgroups, G1/EGFR, G2/FGFR3, G5/PDGFRA and G6/Multi-RTK, totaled over 50% of the cases, underscoring the importance of RTK signaling for glioblastoma pathogenesis." (PMID 38254850, 2024). "In 2012, whole-transcriptome sequencing analysis led to the discovery of recurrent fusions involving the FGFR3 and TACC3 genes as the main oncological driver in a subset of human glioblastomas." (PMID 38067258, 2023). "But we have to keep in mind that among glioblastoma, IDH-wildtype, those that harbor FGFR3::TACC3 fusion display a better prognosis than the others." (PMID 36647073, 2023). "Gliomas with FGFR3::TACC3 fusion mainly occur in adults, display pathological features of glioblastomas (GB) and are usually classified as glioblastoma, IDH-wildtype." (PMID 36647073, 2023). "Regarding pathogenesis of the fusion, in glioblastoma, the FGFR3-TACC3 fusion has been shown to lose a regulatory site for miR-99a, an inhibitor of FGFR3, leading to enhanced expression of the gene fusion." (PMID 35406567, 2022). "The genes most involved in fusions in IDH wild-type glioblastoma are EGFR (6–13%), FGFR3 (3%), MET (1–4%) and the NTRK gene family (1–2%)." (PMID 36002559, 2022). "The first gene fusion discovered was between FGFR3 and the transforming acidic coiled-coil containing protein (TACC3) forming FGFR3-TACC3 in glioblastoma." (PMID 34867402, 2021). "These glioblastoma molecular subgroups are classified as G1/EGFR, G2/FGFR3, G3/NF1, G4/RAF, G5/PDGFRA, G6/Multi-RTK, and G7/Other." (PMID 34572759, 2021). "The G2/FGFR3 subgroup was enriched in female patients, similar to the IDH subgroup, and in contrast to all other glioblastoma subgroups." (PMID 34572759, 2021). "The integrated genomic and transcriptomic analysis of the tumors showed EGFR, PDGFRA, FGFR3, NF1, and BRAF/RAF1 mutually exclusive alterations within the glioblastoma IDH-wild-type category." (PMID 34572759, 2021). "The combined NF1, RAF, and RTK alterations from EGFR, PDGFRA, FGFR3, and Multi-RTK subgroups that activate the ERK/MAPK signaling pathway accounted for 85% of the glioblastoma IDH-wild-type cases." (PMID 34572759, 2021). "The RTK subgroups G1/EGFR, G2/FGFR3, G5/PDGFRA, and G6/Multi-RTK accounted for roughly two-thirds of the glioblastoma IDH-wild-type cases, indicating a major role of RTKs in the pathogenesis of glioblastoma." (PMID 34572759, 2021). "All FGFR3 glioblastoma cases showed chromosome 10 deletion, and the overlap with the F48 10q23.31-qter deletion represented the only common CNV alteration between the FGFR3 and FGFR2 glioblastomas." (PMID 33853673, 2021). "The reality is that the implications of FGFR3 fusion are clear: as previously stated, FGFR3 fusions, most commonly FGFR3-TACC3, are by and large a feature of IDH-wild type glioblastoma, WHO grade IV." (PMID 32085805, 2020). "Fibroblast growth factor receptor 3 (FGFR3)-transforming, acidic coiled-coil containing protein 3 (TACC3) in glioblastoma and chromosome 2 open reading frame 14 (C2orf44)-ALK fusions in colorectal cancer are examples of tandem duplications." (PMID 31007851, 2019). "Intriguingly, oncogenic fusion products between FGFR3 and TACC3 have been identified in glioblastoma, bladder, lung, and nasopharyngeal carcinomas." (PMID 29358577, 2018).
glioblastoma (continued). "Those genes include EGFR, PDGFRA, FGFR3, PIK3CA, MDM4, CDKN2A/B, PTEN and are all members of the core alterated pathways in glioblastoma controlling key phenotypes such as proliferation, apoptosis and angiogenesis." (PMID 25679508, 2015). "Considering the presence of calcifications, differential diagnoses include FGFR3::TACC3 fusion-negative glioblastoma, oligodendroglioma, ependymoma, ganglioglioma, and polymorphous low-grade neuroepithelial tumors of the young (PLNTY)." (PMID 40417325, 2025). "Although these fusions are rare in glioblastoma, the incidence in the Combined cohort being 0.5% for ST7–MET and LMNA–NTRK1, 1.1% for PTPRZ1–MET and GOPC–ROS1, and 1.6% for FGFR3 fusions, they appear to be targetable alterations that also occur in other solid cancers." (PMID 38254850, 2024). "Although antibodies targeting FGFR2 (bemarituzumab, NCT03694522) and FGFR3 (vofatamab, NCT03123055; LY3076226, NCT02529553; MFGR1877S, NCT01363024) are in clinical trials for other cancers, these have yet to be considered for glioblastoma." (PMID 37857607, 2023). "The alterations in FGFR4, KIT, and PEG3 were correlated with a short OS in astrocytoma, alterations in CDK4, FUBP1, and NTRK2 were correlated with a short OS in oligodendroglioma, and alterations in CDK4, CIC, FGFR3, and KMT5B were correlated with a short OS in glioblastoma." (PMID 36998447, 2023). "Moreover, a recent report found that FGFR3 and FGFR4 are also expressed in invasive glioblastoma cells." (PMID 33352931, 2020). "To further characterize gene expression in the Ad-GSCs and Sp-GSCs tumor xenografts, we examined the expression of genes previously defined to be characteristic of the Classical (FGFR3, PDFA, EGFR, AKT-2 and Nestin) and Mesenchymal (CHI3L1, TRADD, NF1, RelB and CASP4) glioblastoma subtypes." (PMID 25955030, 2015). "Molecular analyses can be used to show the fusion between fibroblast growth factor receptor (FGFR3) and transforming acidic coiled coil (TACC) proteins, which most commonly results in progression towards glioblastoma (GBM)." (PMID 41892193, 2026). "There was also an absence of MET amplification and FGFR3 fusion in the de novo RRD glioblastomas." (PMID 38079020, 2023). "A whole genome analysis of more than 2662 adult human glioblastoma samples revealed the number of FGFR-aberrations and amplifications as generally sparse, with prevalence of FGFR1 aberrations of 51 in 3068, FGFR2 in 12 of 2662, FGFR3 in 13 of 2887, and FGFR4 in 9 out of 2456 investigated samples." (PMID 35955806, 2022). "Notably, coarse calcifications in the deep white matter have emerged as a distinctive radiological feature that may aid in differentiating diffuse gliomas with FGFR3::TACC3 fusion from fusion-negative glioblastomas." (PMID 40417325, 2025). "Further studies are needed to compare the frequency and distribution of calcifications in FGFR3::TACC3 fusion-positive and -negative IDH-wildtype glioblastomas." (PMID 40417325, 2025). "In adult setting, patients suffering from a glioblastoma, IDH-wildtype harboring FGFR3::TACC3 fusions have a better survival rate than cases without FGFR3::TACC3 fusion." (PMID 36647073, 2023). "Interestingly, a previous study identified among 79 glioblastomas with FGFR3::TACC3 fusion 11 cases that formed on t-SNE analysis a separate cluster (named ‘outlier’ FGFR3::TACC3 positive glioblastoma, GBM-F3T3-O) close to the cluster of GBM-mesenchymal subtype." (PMID 36647073, 2023).
glioblastoma (continued). "Nonetheless, previous reports have shown that this fusion event is not correlated with FGFR3 mRNA or protein overexpression in Sq-NSCLC, in contrast with glioblastomas." (PMID 36142417, 2022). "In a recent study, the median overall survival of FGFR3::TACC3 fusion-positive glioblastomas was reported to be 31.1 months, significantly longer than that of fusion-negative glioblastomas (19.9 months), with the fusion serving as an independent predictor of better outcome." (PMID 40417325, 2025). "We characterized in this study a spectrum of FGFR alterations from a cohort of 101 WHO grade IV diffuse gliomas, including novel FGFR2 and FGFR3 fusions, the former taking place in IDH-mutant glioblastoma, a neoplasm previously not known to harbor oncogenic FGFR alterations." (PMID 33853673, 2021).